OR1E3 (olfactory receptor family 1 subfamily E member 3 (gene/pseudogene))
Description:
Odorant receptor.
Synonyms: OR17-210; OR1E3P
Gene: Unprocessed pseudogene on chromosome 17 (3,116,427 to 3,117,374, forward strand). Ensembl gene ENSG00000142163.
Subcellular location: Cell membrane
Pathways (Reactome):
Sensory Perception: Expression and translocation of olfactory receptors